MCM2 (minichromosome maintenance complex component 2)
Diseases named in the same sentence as MCM2 in open-access papers (continued):
Sharing a sentence is not in itself a finding about the gene and the disease.
triple-negative breast carcinoma (5 papers, 2015 to 2022). An invasive breast carcinoma which is negative for expression of estrogen receptor (ER), progesterone receptor (PR), and human epidermal growth factor receptor 2 (HER2). "Overexpression of MCM2, MCM3, MCM4, and MCM6 is associated with luminal B, HER2+, and triple-negative breast cancers." (PMID 35401937, 2022). "In triple-negative breast cancer, protein-protein interaction between Mcm2 and Mcm4 was verified with proximity ligation assay." (PMID 32089988, 2020). "Additionally, CDH6 correlated with stem-cell-related transcription factors, including FOXM1, SNAI1, SOX9, and MCM2, in triple-negative breast cancer." (PMID 35938030, 2022). "MCM2 to MCM7 may regulate the synergistic activation of apoptosis in triple negative breast cancer." (PMID 29867845, 2018).
ameloblastoma (4 papers, 2015 to 2022). The most common odontogenic tumor, arising from the epithelial component of the embryonic tooth and usually affecting the molar-ramus region of the mandible or maxilla. "Coincidentally, the expression levels of MCM2 and MCM3 are sensitive markers for predicting aggressive and recurrent behaviors of ameloblastoma." (PMID 28460433, 2017).
breast tumors (4 papers, 2015 to 2020). "Moreover, Roquin1 expression was negatively correlated with CCNE1 and MCM2 in human breast tumors." (PMID 33228782, 2020). "The high expression of Ki-67, MCM2, Cyclin A and PHH3 is also in correlation with high grade and triple negativity, therefore all tested marker seem to be potentially applicable to delineate a patient group with biologically aggressive breast tumors to be suitable to PST." (PMID 31446607, 2020). "As expected, the stem–loop sequences in the 3’UTRs of CCNE1 and MCM2 could be amplified in the GFP antibody pulldown group but not in the group using isotype IgG, indicating the binding of Roquin1 to the 3’UTRs of cell cycle–promoting mRNAs in breast tumor cells." (PMID 33228782, 2020).
Cirrhosis (4 papers, 2009 to 2022). A chronic disorder of the liver in which liver tissue becomes scarred and is partially replaced by regenerative nodules and fibrotic tissue resulting in loss of liver function. "Mcm2 is associated with the progression from cirrhosis to HCC and poor cellular differentiation." (PMID 34583719, 2021). "MCM2, an oncogene, was correlated with the development and progression from cirrhosis to HCC." (PMID 32964028, 2020).
esophageal cancer (4 papers, 2011 to 2020). A primary or metastatic malignant neoplasm involving the esophagus. "MCM6 and MCM2 were revealed to be more accurate and reliable markers in mantle cell lymphoma and esophageal cancer." (PMID 32089988, 2020). "High-MCM2 index has been shown to correlate with high Ki-67 labeling and has been shown to be a prognostic marker in a variety of human malignancies, including cancers of the esophagus, prostate, stomach and in diffuse large B-cell lymphoma." (PMID 21785684, 2011). "The diagnostic values of the individual MCM subunits were identified in various cancers including MCM2 in gastric cardiac cancer and salivary gland tumor, MCM5 in esophageal cancer, MCM7 in meningiomas, and MCM10 in breast cancer." (PMID 32089988, 2020).
invasive breast carcinoma (4 papers, 2005 to 2023). A carcinoma that infiltrates the breast parenchyma. "In practice, most studies, including ours, indicate that triplicate core assessment using a 0.6 mm core size is sufficient for the accurate evaluation of Ki67 and also MCM2 in invasive breast cancer tissue." (PMID 26205655, 2015). "Adhering to these criteria, we carried out a study to evaluate two different methods of assessing Ki67, MCM2 and Geminin IHC in tissue microarrays (TMAs) of a series of consecutive invasive breast cancer cases." (PMID 26205655, 2015). "We have assessed TMAs of 309 cases of primary invasive breast cancers for the expression of the proliferation markers Ki67, MCM2 and Geminin by IHC using conventional light microscopy and by digital imaging." (PMID 26205655, 2015). "To address this question, we compared Ki67, Mcm2 and geminin expression with ER and PR status in an invasive breast carcinoma series (n=120)." (PMID 16278669, 2005). "It thus remains unclear why Ki67 is so utilised in prognostication in invasive breast cancer and other tumours whilst MCM2 is not routinely used." (PMID 26205655, 2015). "MCM2 and TXNRD1 were underexpressed (p < 0.05) in DCIS patient samples but not in invasive breast cancer samples." (PMID 37445737, 2023).
lung squamous cell carcinoma (4 papers, 2020 to 2025). "MCM2 regulates proliferation and cell cycle in lung squamous cell carcinoma, whose overexpressed protein is obviously associated with malign differentiated degree and lymph node metastasis." (PMID 31992202, 2020).
oral cancer (4 papers, 2021 to 2023). "Similarly, aberrant expression of MCM2 in human cau cause development of oral cancer, BC and GC, suggesting that MCM2 is the potential biomarker used to predict the prognosis of certain tumors." (PMID 37305391, 2023). "A recent study also reported that αvβ6, EGFR, CD17, McM2, Geminin and Ki-67 could differentiate oral cancer and HGD with 78% sensitivity." (PMID 37747904, 2023). "This study permitted the proposal of 8 salivary biomarkers for oral cancer in patients previously infected with HPV (RPRD2, PSCA, MCM2, CDKN2A, BAK1, HSPA1A, TANK, MAP2K1)." (PMID 37599356, 2023).
ovarian clear cell cancer (4 papers, 2018 to 2023). An invasive malignant neoplasm that arises from the ovary and is characterized by a predominance of clear and hobnail malignant epithelial cells. "Gulinisha Aihemaiti found that MCM2 was highly expressed in the ovarian clear cell carcinoma, and the expression of MCM2 was mainly confined to nucleus." (PMID 37480569, 2023). "Next, we examined the correlation between subcellular localization of MCM2 and clinico-pathological features, and prognostic factors of patients with ovarian clear cell carcinoma." (PMID 29963273, 2018). "In this study, we showed that MCM2 is highly expressed in clinical samples of ovarian clear cell carcinoma." (PMID 29963273, 2018).
retinoblastoma (4 papers, 2007 to 2018). A malignant tumor that originates in the nuclear layer of the retina. "Expression of ABCG2 and MCM2 has been associated with increased tumor invasiveness in retinoblastoma." (PMID 17615543, 2007). "Apart from cellular stress response proteins, cell cycle proteins such as CDK1, CDK11, MCM2, MCM3, MCM5, and CCNB1 were also found to be hyperphosphorylated in retinoblastoma, implicating accelerated cell cycle progression." (PMID 29914080, 2018).
carcinoma in situ (3 papers, 2003 to 2021). "In contrast, in lesions showing carcinoma in situ (high-grade), Mcm-2 was expressed throughout the epithelium." (PMID 16832409, 2006). "Our histological data show that Mcm-2 is expressed within the most superficial surface layers of laryngeal epithelium in cases of carcinoma in situ and SCC, with minimal expression in abnormal and atypical hyperplasia." (PMID 12966424, 2003). "Importantly, there was minimal expression of Mcm-2 or Ki67 in the most superficial layers of normal larynx and abnormal or atypical hyperplasia, in contrast to carcinoma in situ and SCC." (PMID 12966424, 2003).
colonic adenocarcinomas (3 papers, 2012 to 2022). "The mean MCM2-positive indices of colonic adenocarcinomas in groups 3 (p < 0.001) and 4 (p < 0.001) were significantly lower than that of group 1, indicating that dietary administration with Hrh2 and Hrh3 antagonists decreased cancer cell proliferation." (PMID 26907350, 2016).
diffuse large B-cell lymphoma (3 papers, 2005 to 2020). "The aim of this study was to assess the proliferative activity of diffuse large B-cell lymphoma (DLBCL) in tissue microarray (TMA) using one of the minichromosome maintenance proteins (Mcm2) and to explore its potential value to predict prognosis." (PMID 16368013, 2005).
dysplasia (3 papers, 2006 to 2021). A usually neoplastic transformation of the cell, associated with altered architectural tissue patterns. "The nonparametric receiver operating characteristic analysis suggested that MCM2 and CDC45 had a higher accuracy than CDC6 and CDT1 for distinguishing dysplasia from tongue SCC." (PMID 19116018, 2008). "In addition, it has been reported that telomerase expression was increased in LSIL and HSIL compared to NSIL samples, and increased expression of MCM2 and TOP2A (ProExC) was correlated with dysplasia and severity of cervical lesions." (PMID 33413211, 2021).
Fanconi anemia (3 papers, 2021 to 2025). Fanconi anemia (FA) is a hereditary DNA repair disorder characterized by progressive pancytopenia with bone marrow failure, variable congenital malformations and predisposition to develop hematological or solid tumors. "Subsequently, TARIP has been shown to ubiquitylate the replicative CMG (CDC45/MCM2–7/GINS) helicase, thereby regulating the NEIL3 pathway and Fanconi anemia pathway in the DNA interstrand crosslink repair process." (PMID 34349117, 2021).
gallbladder cancer (3 papers, 2016 to 2023). "The main result of this study is that KNTC1 and MCM2 genes are highly expressed in gallbladder carcinoma." (PMID 37480569, 2023). "In gallbladder cancer, MCM2 has been shown to serve as an independent predictor of poor outcome, since expression of MCM2 was correlated with larger tumor mass, poor differentiation, lymph node metastasis and shorter survival." (PMID 26623561, 2016). "KNTC1 and MCM2 may be molecular targets for early diagnosis and precise treatment of gallbladder cancer, and provide a basis for the study of the mechanism of gallbladder cancer." (PMID 37480569, 2023). "The public datasets were used to validate roles of KNTC1 and MCM2 in gallbladder cancer." (PMID 37480569, 2023). "This is consistent with results of previous studies, which speculated that MCM2 may play a role in progression of gallbladder cancer." (PMID 37480569, 2023). "Similarly, in our study, we also found that the MCM2 gene is highly expressed in gallbladder cancer, and higher the MCM2, worse the prognosis." (PMID 37480569, 2023). "However, relationship between KNTC1 and MCM2 and gallbladder cancer is unclear." (PMID 37480569, 2023). "Gene expression heat map showed that KNTC1, MCM2, CKAP2, RACGAP1, CCNB1 were highly expressed in gallbladder carcinoma samples." (PMID 37480569, 2023). "We found that five core genes (KNTC1, MCM2, CKAP2, RACGAP1, CCNB1) were highly expressed in gallbladder carcinoma samples and low in normal samples." (PMID 37480569, 2023). "However, the relationship between KNTC1, MCM2 genes and gallbladder cancer is not clear." (PMID 37480569, 2023).
HIV-1 infection (3 papers, 2012 to 2022). The type species of lentivirus and the etiologic agent of acquired immunodeficiency syndrome (AIDS). "This compound could use three targets (ESR1, ESR2 and SERPINB9) to regulate MCM2-TUBB2A, of which MCM2 can effectively block HIV-1 infection of macrophages by inhibiting viral DNA synthesis." (PMID 36534703, 2022).
laryngeal squamous cell carcinoma (3 papers, 2003 to 2021). A squamous cell carcinoma that arises from the larynx. "A number of studies have shown MCM2 expression to be a significant prognostic marker in other tumour types including oesophageal and laryngeal squamous cell carcinoma and oligodendroglioma of the brain." (PMID 26205655, 2015). "We present the conceptual study investigated the capacity of minichromosome maintenance-2 (MCM-2), Ki-67, and epidermal growth factor receptor (EGFR) to assess the severity and progression of laryngeal squamous cell carcinoma (LSCC) disease and to study the correlations among these markers." (PMID 34272446, 2021). "Sections of normal larynx (n=10), laryngeal dysplasia (n=20) and laryngeal squamous cell carcinoma (SCC) (n=10) were classified according to the Ljubljana classification and stained for markers of cell cycle entry, minichromosome maintenance protein-2 (Mcm-2) and Ki67." (PMID 12966424, 2003).
ovarian neoplasm (3 papers, 2004 to 2015). A benign, borderline, or malignant neoplasm involving the ovary. "Taken together, our data suggest that cyclin A expression can be used as a surrogate immunohistochemical marker of S phase and that the cyclin A/Mcm2 ratio in ovarian neoplasms can be used to estimate the fraction of cycling cells that are in the S phase." (PMID 15083189, 2004). "The proliferative subtype was identified by the overexpression of transcription factors HMGA2 and SOX11, proliferation marker genes such as MCM2 and PCNA, and underexpression of MUC1 and MUC16, which are known ovarian tumor marker genes." (PMID 25611546, 2015). "In the present study, we have clearly demonstrated the nuclear localisation of MCM-2 and MCM-5 proteins in ovarian neoplasms." (PMID 17940502, 2007).
small cell lung carcinoma (3 papers, 2020 to 2022). Small cell lung cancer (SCLC) is a highly aggressive malignant neoplasm, accounting for 10-15% of lung cancer cases, characterized byrapid growth, and early metastasis. "Proteomic analysis of clinical specimens of high-grade small cell lung cancer showed that MCM2 was associated with a poor prognosis in patients." (PMID 32420375, 2020).
viral infection (3 papers, 2010 to 2020). "The repression of MCM2, MCM3, MCM5, and MCM7 was associated with viral infection previously, but detailed functional studies have not been carried out." (PMID 28912786, 2017). "This difference between wild type and mutant virus infection was apparent for both MCM2 and MCM4, although the effect on MCM4 was greater." (PMID 20333247, 2010).
Alzheimer disease (2 papers, 2022 to 2023). A progressive, neurodegenerative disease characterized by loss of function and death of nerve cells in several areas of the brain leading to loss of cognitive function such as memory and language. "We also identified genes such as PTPN11 (also known as protein tyrosine phosphatase SHP2), and MCM2, involved in cell maintenance and renewal, which have been characterized as risk factors for Alzheimer’s Disease." (PMID 39086978, 2022). "Previous studies have shown that inhibition of MCM2 reduces cell viability and aggravates apoptosis in cellular models of Alzheimer’s disease." (PMID 37480569, 2023).
astrocytoma (2 papers, 2009 to 2013). "Actually, there is scarce knowledge about the value of Mcm2 in low-grade astrocytomas, so further studies are highly desired to fully establish its clinical significance in these tumours." (PMID 23618321, 2013). "The wide range of Mcm2 PIs points to possible overlap of values between astrocytomas of various malignancy grades comparable with that of Ki67/MIB-1 immunostaining." (PMID 23618321, 2013). "In our hands Mcm2 immunostaining has no advantage over Ki67/MIB-1 in the evaluation of grade II astrocytomas." (PMID 23618321, 2013). "Accordingly, Mcm2 does not seem to have any advantages over Ki67/MIB-1 in the evaluation of the prognosis of grade II astrocytomas." (PMID 23618321, 2013).
Barrett esophagus (2 papers, 2009 to 2020). Esophageal lesion lined with columnar metaplastic epithelium which is flat or villiform. "This has also been observed in studies of Mcm2 and Ki67 in Barrett's oesophagus and in neoplastic oesophagus using Mcm5." (PMID 19293805, 2009).
cervical disease (2 papers, 2018 to 2021). "•We assessed the performance of a dual biomarker (one viral: HPVE4, one cellular: MCM2) in risk stratification of cervical disease." (PMID 30218891, 2018).
cervical squamous cell carcinoma (2 papers, 2013 to 2023). A squamous cell carcinoma arising from the cervical epithelium. "A significant expression pattern was obtained for MCM genes MCM2-10 in cervical squamous cell carcinoma and endocervical adenocarcinoma." (PMID 39086679, 2023).
clear cell carcinoma (2 papers, 2016 to 2018). "Therefore, immunohistochemical localization studies of MCM2 were performed in association with cellular apoptosis in clear cell carcinoma." (PMID 29963273, 2018). "Although MCM2 was mostly localized to the nuclei of cancer cells, a subset of clear cell carcinoma samples exhibited cytoplasmic localization of MCM2 in addition to nuclear staining." (PMID 29963273, 2018). "As expected, clear cell carcinoma cells with cytoplasmic expression of MCM2 exhibited significantly higher apoptotic cell ratio than that of cells with nuclear MCM2 expression." (PMID 29963273, 2018). "The MCM2-positive cell ratio was significantly higher in clear cell carcinoma with cytoplasmic/nuclear staining (CCC-C) than in serous carcinoma, endometrioid carcinoma, and clear cell carcinoma with nuclear staining (CCC-N) (P < 0.01, P < 0.01, P < 0.05, respectively)." (PMID 29963273, 2018). "In addition, cytoplasmic MCM2 expression provides a key indicator of the effectiveness of MCM2-targeted therapy against clear cell carcinoma in the future." (PMID 29963273, 2018). "Therefore, cytoplasmic localization of MCM2 significantly correlated with increased apoptosis in clear cell carcinoma cells, resulting in improved prognosis." (PMID 29963273, 2018). "We demonstrated cytoplasmic expression of MCM2 in a subset of clear cell carcinoma cases." (PMID 29963273, 2018). "Furthermore, recurrence and MCM2 localization were independent factors influencing the overall survival of clear cell carcinoma cases, as determined by multivariate analysis." (PMID 29963273, 2018).
epilepsy (2 papers, 2018 to 2021). A brain disorder characterized by episodes of abnormally increased neuronal discharge resulting in transient episodes of sensory or motor neurological dysfunction, or psychic dysfunction. "MCM2+ NEC were present in all zones in epilepsy cases and with significantly higher proliferative fractions of 6.6% compared with 3.3% in controls." (PMID 28925561, 2018). "Nestin+/MCM2+ were more numerous in epilepsy cases than non‐epilepsy controls (p < .0001); Bipolar/radial glial‐like MCM2+ NEC were present in 56% of surgical epilepsy cases compared with 20% of controls." (PMID 28925561, 2018). "Of note, bipolar NEC in the WM were MCM2+ in over half the epilepsy cases compared with only 20% of controls." (PMID 28925561, 2018). "Expressed as a proliferative fraction, 5.3% of NEC were MCM2+ in epilepsy cases." (PMID 28925561, 2018).
epithelial dysplasia (2 papers, 2006 to 2008). "In this study, we found that CDC6, CDT1, MCM2 and CDC45 mRNA expression analyzed by quantitative real-time PCR are significantly higher in malignant SCC than mild precancerous epithelial dysplasia, and the expression levels in general increase with increasing grade of dysplasia." (PMID 19116018, 2008).
Hearing impairment (2 papers, 2015 to 2022). A decreased magnitude of the sensory perception of sound. "Segregation of the 10 missense variants was examined within this pedigree, and only one variant in exon 2 of MCM2 gene (c.130C>T, p.R44C) segregated perfectly with hearing loss." (PMID 26196677, 2015). "We had found six patients with hearing loss at the beginning and considered that this variant in MCM2 showed reduced penetrance after variant screening of the 13 family members." (PMID 26196677, 2015). "In summary, we have identified MCM2 as a novel gene responsible for nonsyndromic hearing loss of autosomal dominant inheritance in a Chinese family." (PMID 26196677, 2015). "And variant MCM2 knock-in animal models constructed in the future may help verify the relationship between variant MCM2 and phenotype of hearing loss." (PMID 26196677, 2015). "We also tentatively detected effects of variant MCM2 in cell apoptosis, cell proliferation and cell cycle phases in HEK293 to pursue mechanism of this variant gene leading to hearing loss." (PMID 26196677, 2015).